DUOX2 (dual oxidase 2)
Description:
Generates hydrogen peroxide which is required for the activity of thyroid peroxidase/TPO and lactoperoxidase/LPO. Plays a role in thyroid hormone synthesis. Also required for lactoperoxidase-mediated antimicrobial defense at the surface of mucosa. Synthesizes NAADP from its reduced NAADPH form which promotes Ca(2+) signaling during T cell activation. May have its own peroxidase activity through its N-terminal peroxidase-like domain.
Synonyms: LNOX2; THOX2; P138-TOX; P138(TOX); NOXEF2; TDH6
Tractability: Antibody: UniProt places it where antibodies can reach, with high confidence; its Gene Ontology location is reachable by antibodies, with high confidence; UniProt predicts a signal peptide or a membrane-spanning region. PROTAC: a small molecule that binds it is known.
Target class: Transmembrane 1-electron transfer carriers; Transporter
Gene: Protein-coding gene on chromosome 15 (45,092,650 to 45,114,172, reverse strand). Ensembl gene ENSG00000140279.
Subcellular location: Apical cell membrane; Cell junction
Pathways (Reactome):
Metabolism: Thyroxine biosynthesis
Gene Ontology:
Molecular function: calcium ion binding; NAD(P)H oxidase H2O2-forming activity; protein binding; superoxide-generating NAD(P)H oxidase activity; heme binding; oxidoreductase activity; peroxidase activity
Biological process: cytokine-mediated signaling pathway; hydrogen peroxide biosynthetic process; positive regulation of cell motility; positive regulation of wound healing; response to cAMP; response to virus; superoxide anion generation; cuticle development; defense response; regulation of thyroid hormone generation; cellular oxidant detoxification; cellular response to cytokine stimulus; response to oxidative stress; thyroid hormone generation
Cellular component: anchoring junction; apical part of cell; apical plasma membrane; cell leading edge; cell surface; cytosol; endoplasmic reticulum; extracellular exosome; NADPH oxidase complex; plasma membrane
Genetic constraint (gnomAD): Loss-of-function variants: 182 observed, 176.7 expected, observed/expected ratio (o/e) 1.03, 90% interval 0.91 to 1.16. The upper end of that interval is the gene's LOEUF score, 1.16, which puts it in group 5 of 6, group 1 being the genes least tolerant of losing a copy. Missense variants: 1,971 observed, 1,975.1 expected, observed/expected ratio (o/e) 1, 90% interval 0.96 to 1.04. Synonymous variants: 769 observed, 790 expected, observed/expected ratio (o/e) 0.97, 90% interval 0.92 to 1.03.
Homologues: Orthologues: chimpanzee DUOX2 (99% identical), macaque DUOX2 (97% identical), rabbit DUOX2 (86% identical), pig DUOX2 (86% identical), mouse Duox2 (85% identical), guinea pig DUOX2 (83% identical), rat Duox2 (82% identical). Paralogues in human: DUOX1 (78% identical), NOX5 (13% identical), NOX3 (11% identical), CYBB (11% identical), NOX1 (11% identical), NOX4 (10% identical).
Diseases named in the same sentence as DUOX2 in open-access papers:
DUOX2 is named in the same sentence as 123 diseases in open-access papers, as found by Europe PMC text mining. Sharing a sentence is not in itself a finding about the gene and the disease. The quoted sentences say what the papers report.
congenital hypothyroidism (38 papers, 2010 to 2025). A thyroid hormone deficiency present from birth. "The most frequently affected gene was DUOX2, with 11 distinct variants identified in 10 patients (31.3%), reinforcing its central role in dyshormonogenesis-associated congenital hypothyroidism in our study." (PMID 40362701, 2025). "Studies have shown that mutations in DUOX2 can initiate CH, but the clinical phenotype, primarily the manifestation of transient congenital hypothyroidism, is variable." (PMID 39728398, 2024). "Genetic variants in DUOX2 can cause partial to total iodination organification defects and clinical heterogeneity, from transient to permanent congenital hypothyroidism." (PMID 39126042, 2024). "The defect of such apparatus produces dramatic impairment of thyroid function, as demonstrated by the presence of congenital hypothyroidism in patients carrying mutations in the DUOX2 gene." (PMID 36834830, 2023). "Functional analysis confirmed that this DUOX2 variant was a loss-of-function missense substitution and the primary cause of congenital hypothyroidism." (PMID 36028527, 2022). "A secondary finding in this fetus was a homozygous frameshift variant in DUOX2 leading to congenital hypothyroidism." (PMID 34974531, 2022). "Another interesting example of a combination with less evident proof is the oligogenic combination OLI474, associated with congenital hypothyroidism, derived from a cohort study and involving three heterozygous variants in the genes DUOX2, TG and TPO." (PMID 35411390, 2022). "Surprisingly, one girl had a compound heterozygous variant (c.1588A>T and c.1462G>A) in the DUOX2 gene, which is a well-known pathogenic gene associated with congenital hypothyroidism (CH)." (PMID 34794485, 2021). "In light of our findings, we suggest that the mutant caused by the D409G mutation in DUOX2 would provide a valuable resource for the study of molecular pathogenesis and possible treatments for human congenital hypothyroidism." (PMID 30651277, 2019). "In humans, DUOX2 gene mutations can produce a spectrum of congenital hypothyroidism with an autosomal recessive inheritance." (PMID 30651277, 2019). "For instance, biallelic and triallelic mutations in DUOX2 are associated with permanent congenital hypothyroidism, whilst mononoallelic mutation caused transient congenital hypothyroidism." (PMID 28222800, 2017). "With regard to ethnicity, for example, DUOX2 appears to be the most commonly implicated gene in East Asian populations, with DUOX2 variants reported in 16–32% of congenital hypothyroidism patients in Korea, Japan, and China." (PMID 29026407, 2017). "Mutation p.Lys530* and p.Arg1110Gln in DUOX2 were found in patients with transient congenital hypothyroidism." (PMID 28222800, 2017). "Whole-exome sequencing in siblings with a known homozygous DUOX2 mutation and unusually marked congenital hypothyroidism (CH) identified the human homozygous DUOX1 mutation, segregating with CH." (PMID 28633507, 2017). "DUOX2 is reported to be involved in thyroid hormone synthesis, and missense mutation of DUOX2 results in congenital hypothyroidism." (PMID 28095923, 2017). "In studies of congenital hypothyroidism (CH), DUOX2 mutations have been extensively explored." (PMID 40830794, 2025). "Mutation in Dual oxidase 2 (DUOX2) gene in humans leads to congenital hypothyroidism." (PMID 33685490, 2021). "In addition, consistent with findings in human patients with congenital hypothyroidism, our results indicated that the DUOX2 gene variant can lead to a severe disruption of H2O2-generating activity." (PMID 30651277, 2019). "As DUOX2 mutations have been reported to play a pathogenic role in human congenital hypothyroidism, we thus investigated whether p.D409G also causes thyroid hormone deficiency in pigs." (PMID 30651277, 2019). "DUOX2/DUOXA2 defects can cause congenital hypothyroidism (CH), but it is unknown whether DUOX1/DUOXA1 mutations can also cause CH." (PMID 31428054, 2019).
congenital hypothyroidism (continued). "It has been well documented that mutations in DUOX2 are associated with congenital hypothyroidism." (PMID 28222800, 2017). "More recently, the first evidence of a physiologic role for DUOX1 in humans was provided by a report of two siblings with homozygous inactivating mutations in both DUOX1 and DUOX2 associated with congenital hypothyroidism more severe than is typically observed in DUOX2 deficiency alone." (PMID 29026407, 2017). "Our analysis suggested that the DUOX2 compound heterozygous mutations in both sisters may be involved in permanent congenital hypothyroidism, and correlated with significant goiter manifestation at a young age." (PMID 28222800, 2017). "Mutations in the DUOX2 gene are linked to congenital hypothyroidism in humans and mice." (PMID 23028364, 2012). "Indeed, mutations in DUOX1 and DUOX2 have been linked with congenital hypothyroidism." (PMID 30700401, 2019). "Similarly, the prevalence of DUOX2 variants in Italy has been reported as 15% in unselected patients with congenital hypothyroidism, 23% in those with a eutopic thyroid gland, and to 30–37% in those with a eutopic gland and a documented partial iodine organification disorder." (PMID 29026407, 2017). "Loss-of-function mutations in DUOX2 or DUOXA2 genes disrupt H2O2 generation, impairing thyroid hormone synthesis and resulting in congenital hypothyroidism." (PMID 40362701, 2025). "Unsurprisingly, the phenotypes associated with duox and cyba mutations in zebrafish were consistent with mutations in the human orthologs of these genes, with DUOX2 and CYBA, leading to congenital hypothyroidism and chronic granulomatous disease, respectively." (PMID 36843843, 2023). "In Chinese patients with congenital hypothyroidism, seven genetic variants of TSHR, such as mutations in Ile216, Ala275, Asn372, and Ser567 with loss-of-function, and genetic variants of DUOX2 are also found." (PMID 37686882, 2023). "By Angel Care GS, we detected two heterozygous and one homozygous pathogenic mutations in the DUOX2 gene which associated with TDH6 and congenital hypothyroidism (CH)." (PMID 37147621, 2023). "Whereas bi-allelic mutations in DUOX2 and DUOXA2 cause congenital hypothyroidism, heterozygous DUOX2 variants have been implicated in inflammatory bowel disease (IBD)." (PMID 36166305, 2022). "The coexistence of mutations in the dual oxidase maturation factor 2 (DUOXA2) and dual oxidase 2 (DUOX2) genes is rarely identified in congenital hypothyroidism (CH)." (PMID 26758695, 2016). "The dual oxidase maturation factor 2 (DUOXA2) and dual oxidase 2 (DUOX2) genes are rarely identified in congenital hypothyroidism (CH)." (PMID 26758695, 2016). "Mutations in the DUOXA2, DUOX2, and TPO genes are responsible for thyroid dyshormonogenesis and goitrous congenital hypothyroidism (GCH)." (PMID 26758695, 2016). "Similar to DUOX2, missense mutations in the DUOXA2 gene were found in patients with congenital hypothyroidism." (PMID 23028364, 2012). "We propose that the underlying etiology of congenital hypothyroidism (CH) in the proband is attributable to the combination of a DUOX2 gene mutation and ectopic thyroid, rather than a mutation in the MAN1B1 gene." (PMID 41393301, 2025). "DUOX2 is a known causative gene for congenital hypothyroidism, but this particular variant has not been previously reported." (PMID 36028527, 2022). "In addition, a congenital hypothyroidism might have a digenic cause; digenic DUOX1 and DUOX2 causative variants in cases with congenital hypothyroidism have been reported." (PMID 34200080, 2021). "Earlier studies also have shown that p.Arg1110Glu in DUOX2 reduced H2O2 production (5–9%, P < 0.01), hence contributed towards transient congenital hypothyroidism." (PMID 28222800, 2017). "Although dual oxidase 1 (DUOX1) is highly homologous to DUOX2, isolated defects of DUOX1 have not been reported to cause congenital hypothyroidism." (PMID 29026407, 2017).
hypothyroidism (31 papers, 2011 to 2025). Abnormally low levels of thyroid hormone. "The risk of developing hypothyroidism is increased in cases of monoallelic dual oxidase 2 (DUOX2) variant, hypothyroidism, or preterm birth." (PMID 39940256, 2025). "An increase in DUOX2 expression affects intestinal immune homeostasis in mice, and mutations in DUOX2 can lead to hypothyroidism." (PMID 40052788, 2025). "Eighteen patients with pathogenic variants in the DUOX2 gene were eventually diagnosed with hypothyroidism." (PMID 39728398, 2024). "DUOX2 is essential for thyroid hormone synthesis and this specific hypothyroidism has been attributed to the presence of a unique mutation in the DUOX2 gene of the giant panda." (PMID 37595375, 2023). "Previous studies demonstrated that biallelic DUOX2 mutations cause severe, permanent hypothyroidism, while monoallelic mutations result in milder, transient hypothyroidism." (PMID 32565793, 2020). "Further studies are needed to determine the duration of this early overt hypothyroidism, which has previously been reported in association with DUOX2 or DUOXA2 mutations and which eventually resolves." (PMID 31044655, 2019). "As a separate thyroid peroxidase is needed for the synthesis of thyroxine by Duox2, the functionality and requirement of the peroxidase domain of DUOX2 is also somewhat controversial, as judged from congenital forms of thyroid deficiency." (PMID 30084091, 2018). "Defects in DUOX2 cause severe, permanent CH due to complete disruption of thyroid hormone synthesis or milder, transient hypothyroidism caused by insufficient quantities of thyroid hormones." (PMID 29435108, 2018). "In humans and mice, DUOX2 loss-of-function mutations can lead to hypothyroidism." (PMID 36978520, 2023). "It is likely that the paternal isodisomy in this patient resulted in simultaneous loss of heterozygosity in the imprinting UBE3A gene and the paternally derived pathogenic DUOX2 E520D missense substitution, resulting in a complex clinical phenotype, i.e., Angelman syndrome with hypothyroidism." (PMID 36028527, 2022). "OMIA 002210-9823 is associated with hypothyroidism and congenital and DUOX2-related disorders in Sus scrofa, and may play a role in severe thyroid hormone deficiency in pigs." (PMID 34440604, 2021). "Anecdotal reports describe fluctuating thyroid status over time with DUOX2 dysfunction, suggesting that both patients and mutation-carrying relatives should be counseled regarding possible future risk of hypothyroidism, particularly during pregnancy when iodine status can also be compromised." (PMID 31044655, 2019). "Dual oxidase 2 (DUOX2) mutations may initially cause borderline elevation of bsTSH, which later evolves into significant hypothyroidism on venous blood measurement." (PMID 31044655, 2019). "However, studies have reported biallelic inactivating DUOX2 mutations in cases of mild hypothyroidism." (PMID 29435108, 2018). "Mutation of DUOX2 causes hypothyroidism because of insufficient H2O2 production." (PMID 29435108, 2018). "TG mutations may result in euthyroid goiter and mild or severe hypothyroidism, and monoallelic and biallelic DUOX2 mutations may both cause permanent or transient CH." (PMID 27525530, 2016). "Additionally, in murine models, only DUOX2 loss of function is associated with hypothyroidism; thus, the role of DUOX1 in thyroid biology remains unclear." (PMID 28633507, 2017). "Furthermore, DUOX2 compound heterozygous mutation may be associated with early onset of hypothyroidisms and goiter." (PMID 28222800, 2017). "In the present study, TSHR variations mainly present with severe hypothyroidism, while DUOX2 variations were less common." (PMID 41133710, 2025). "Genes related to TH biogenesis show a normal response to TSH stimulation in hypothyroidism, including Tpo, Pendrin, Tshr, Nis, Mct8, Duox1, Duox2, Duoxa1, and Duoxa2." (PMID 35326426, 2022).
hypothyroidism (continued). "The ChIP data showed a predominant pattern of reduced CREB binding on the Duox2 promoter in euthyroid and hyperthyroid conditions in K146Q mice and enhanced in hypothyroidism." (PMID 34237030, 2021). "Since DUOX2 variants are found at high frequencies among healthy populations, it has been postulated that DUOX2 and DUOXA2 mutations may predispose to hypothyroidism in the setting of genetic or environmental modulators but are not directly causative." (PMID 39413214, 2024). "Unlike in humans, DUOX2 loss of function is associated with severe, permanent CH in murine models and is also thought to mediate the permanent hypothyroidism and slow metabolic rate seen in giant pandas." (PMID 35588090, 2022). "Defects in the DUOX2/DUOXA2 heterodimer lead to hypothyroidism and goiter." (PMID 26758695, 2016). "However, because hypothyroidism due to DUOX2 mutations tends to be relatively mild, it has been suggested that DUOX1 may partly compensate for DUOX2 deficiency." (PMID 29026407, 2017). "This concept finds support in the established genetics of CH, where variations in genes like DUOX2 and DUOXA2 can present as either PCH or TCH hypothyroidism." (PMID 41480151, 2025). "Inactivating NADPH oxidase variants discovered in patients with chronic granulomatous disease and hypothyroidism have greatly enhanced our understanding of structure-function relationships in NOX2 and DUOX2 complexes." (PMID 37820403, 2023). "The TF DNA binding pattern in Duox2 promoter was similar to that seen on the Tg promoter; that is, K146Q mice showed reduced NCoR and CREB binding in hyperthyroidism and enhanced binding with hypothyroidism, compared with WT mice." (PMID 34237030, 2021). "This hypothesis has been supported by the fact that mice lacking function of both DUOX enzymes have more severe hypothyroidism than those lacking only DUOX2." (PMID 29026407, 2017). "Additionally, in murine models, only DUOX2, and not DUOX1, loss of function is associated with hypothyroidism; thus, the role of DUOX1 in thyroid biology remains unclear." (PMID 35588090, 2022).